LRPPRC (leucine rich pentatricopeptide repeat containing)
Diseases named in the same sentence as LRPPRC in open-access papers (continued):
Sharing a sentence is not in itself a finding about the gene and the disease.
breast carcinoma (10 papers, 2020 to 2025). "Breast Cancer Gene-Expression Miner v4.5 showed that LRPPRC level was negatively associated with ER and PR expression, while METTL16, RBM15B, ZC3H13 level was positively linked with ER and PR expression." (PMID 33362863, 2020). "LRPPRC aggravates inflammation to promote malignancy of breast cancer cell through increasing the m6A modification of C-X-C motif chemokine ligand 11 (CXCL11)." (PMID 40555877, 2025). "Compared to normal tissues, the expression level of LRPPRC protein was also increased in breast cancer tissues." (PMID 38372449, 2024). "Simultaneously, we detected the expression of LRPPRC in normal breast epithelial cell line and breast cancer cell lines." (PMID 38372449, 2024). "We then examined the expression of the LRPPRC protein in breast cancer by searching Clinical Proteomic Tumor Analysis Consortium (CPTAC) database." (PMID 38372449, 2024). "In HER-2 (+) breast cancer patients, the expression of LRPPRC, METTL16, RBM15B, and ZC3H13 were all lower than the HER-2 (−) group." (PMID 33362863, 2020). "According to the clinical database of breast cancer of TCGA, RBM15B, YTHDF3, ZC3H13, METTL16, and LRPPRC were picked up indicating strong associations with clinical characteristics." (PMID 33362863, 2020). "The results in breast cancer patients showed that the relatively high expression of YTHDF3 and LRPPRC were remarkably associated with worse RFS, whereas relatively high expression of RBM15B, ZC3H13, and METTL16 had better RFS." (PMID 33362863, 2020). "In HER-2 (+) breast cancer patients, LRPPRC, METTL16, RBM15B, and ZC3H13 expressed lower than the HER-2 (−)." (PMID 33362863, 2020). "Notably, LRPPRC mRNA expression was elevated in breast cancer tissues relative to that in normal tissues." (PMID 38372449, 2024). "Interestingly, the expression level of LRPPRC mRNA was specifically upregulated in TNBC compared to other breast cancer subtypes." (PMID 38372449, 2024). "Moreover, LRPPRC protein expression was significantly higher in TNBC than in other breast cancer subtypes." (PMID 38372449, 2024). "Therefore, we examined the expression of LRPPRC mRNA in breast cancer by searching The Cancer Genome Atlas (TCGA) database." (PMID 38372449, 2024). "LRPPRC showed the highest expression in basal-like breast cancer subtype." (PMID 33362863, 2020). "The immunohistochemical detection of several types of cancers, including lung adenocarcinoma, breast cancer, oesophageal squamous cell cancer, gastric adenocarcinoma, etc., shows that LRPPRC is abundantly expressed in cancer tissues in contrast to the adjacent normal tissues." (PMID 33362863, 2020). "In addition to its involvement with copper, LRPPRC, which contributes to the stability and active expression of complex IV mRNA, is highly expressed in various tumor tissues, including ovarian cancer, breast cancer, lung cancer, and gastric cancer." (PMID 41516324, 2025). "Meanwhile, IHC staining showed that the expression patterns of the breast cancer markers ER, PR, HER2 and LRPPRC were well preserved in PDO/PDX models and parental tumour tissues." (PMID 38372449, 2024). "At the clinical level, we verified the roles of LRPPRC in CDK4/6i treatment response by Immunohistochemical (IHC) experiment using samples from breast cancer patients, as breast cancer is the only approved clinical application for CDK4/6i." (PMID 37452037, 2023). "The high expression of YTHDF3, ZC3H13, LRPPRC, and METTL16 indicated poor survival rate in patients with breast cancer, while high expression of RBM15B pointed to a better survival rate." (PMID 33362863, 2020). "From another perspective, Kaplan-Meier Plotter platform showed that the relatively high expression of YTHDF3 and LRPPRC and the relatively low expression of RBM15B, ZC3H13, and METTL16 in breast cancer patients had worse Relapse-Free Survival (RFS)." (PMID 33362863, 2020).
breast carcinoma (continued). "Moreover, whether LRPPRC plays an essential role in luminal and HER2‐positive breast cancer warrants further investigation." (PMID 38372449, 2024).
gastric cancer (8 papers, 2014 to 2025). A primary or metastatic malignant neoplasm involving the stomach. "The in vitro proliferation assay showed that LRPPRC expression is inversely associated with gastric cancer cells growth." (PMID 24375316, 2014). "The present in vitro study showed that LRPPRC expression is associated with tumor growth, and the inhibition of LRPPRC may lead to a reduction in gastric cancer proliferation." (PMID 24375316, 2014). "High expression of LRPPRC is related to poor prognosis in prostate cancer patients, consistent with data obtained with gastric cancer." (PMID 37496051, 2023). "The primary aim of this study was to determine LRPPRC expression and its correlation with clinicopathological, characteristics, and prognosis of patients with gastric cancer." (PMID 24375316, 2014). "In conclusion, our results suggested that LRPPRC is a novel independent marker for the prognosis with functional relevance in gastric cancer." (PMID 24375316, 2014). "Our results showed that LRPPRC expression in gastric cancer tissues is significantly higher than that in paired control tissue (P < 0.001)." (PMID 24375316, 2014). "The expression of LRPPRC was verified by immunohistochemistry in gastric cancer and corresponding normal tissues." (PMID 24375316, 2014). "To investigate the potential oncogenic role of LRPPRC in gastric cancer, we first examined the expression level of LRPPRC in a series of paired gastric cancer tissues with the adjacent nonneoplastic tissues." (PMID 24375316, 2014). "According to LRPPRC expression status, we divided the gastric cancer samples into three groups for the clinicopathological evaluation." (PMID 24375316, 2014). "The correlation between LRPPRC and clinicopathological features in gastric cancer was further evaluated." (PMID 24375316, 2014). "The similar result was obtained in other studies showing that LRPPRC protein was indeed relatively upregulated in gastric cancer and others carcinoma tissues." (PMID 24375316, 2014). "We found that positive LRPPRC expression in gastric cancer tissues (219/253, 86.6 %) was significantly higher than that in paired noncancerous tissues (132/253, 52.2 %)." (PMID 24375316, 2014). "In summary, our results show that high LRPPRC protein expression is correlated with the depth of tumor infiltration and is an unfavorable independent prognostic factor for surgically resected gastric cancer." (PMID 24375316, 2014). "We analyzed LRPPRC gene expression in 253 paired cases of gastric cancer and noncancerous regions and six gastric cancer cell lines to demonstrate the importance of LRPPRC expression for the prediction of prognosis of gastric cancer." (PMID 24375316, 2014). "Besides, an in vitro study was performed to observe the LRPPRC effect on gastric cancer cell proliferation." (PMID 24375316, 2014). "Furthermore, elevated levels of LRPPRC predict shorter overall survival in patients with prostate adenocarcinomas or gastric cancer." (PMID 24722279, 2014). "Our results indicated that LRPPRC could be used as a predictive marker for patient prognosis of gastric cancer and may be a novel therapeutic target for gastric cancer in future." (PMID 24375316, 2014). "We first examined the expression of LRPPRC in six gastric cancer cell lines by Western blot." (PMID 24375316, 2014). "However, the LRPPRC expression in gastric cancer and its correlation with gastric cancer clinicopathological characteristics is still unclear." (PMID 24375316, 2014). "The overall survival analysis using the Kaplan-Meyer method revealed that the prognosis of gastric cancer patients whose tumors with higher or moderate LRPPRC expression showed significantly shorter survival than those with no or weak LRPPRC expression (P < 0.001)." (PMID 24375316, 2014). "The metastasis mechanism of LRPPRC in gastric cancer may involve a multitude of epigenetic pathways and needs to be addressed in the future." (PMID 24375316, 2014).
gastric cancer (continued). "Furthermore, a Multivariate analysis indicated that lymph node metastasis (N P = 0.004), distant metastasis (M P = 0.002), TNM stage (P = 0.017), and LRPPRC expression (P = 0.004) were independent prognostic factors of overall survival for the patients with gastric cancer." (PMID 24375316, 2014). "Our results showed that LRPPRC protein level was higher expressed in gastric cancer cell line SGC7901, BGC823, MKN45, and XGC9811 as compared with the other gastric cancer cell lines." (PMID 24375316, 2014). "Because LRPPRC expression was higher in gastric cancer tissues than that in paired noncancer tissues, six gastric cancer cell lines were chosen for the proliferation study." (PMID 24375316, 2014). "LRPPRC expression was investigated by immunohistochemistry in 253 gastric cancer tissues and paired noncancerous tissues." (PMID 24375316, 2014). "The difference in LRPPRC staining between gastric cancer tissues and paired noncancerous tissues was statistically significant (P < 0.001)." (PMID 24375316, 2014). "There have been some studies on the prognostic impact of tumor markers in gastric cancer, but the previous studies have not evaluated the relevance in LRPPRC expression and tumor prognosis." (PMID 24375316, 2014). "In this study, we first examined LRPPRC expression in 253 paired cases of gastric cancer and paired noncancerous regions and six gastric cancer cell lines to investigate the relevance of LRPPRC expression and its relation to clinicopathological characteristics." (PMID 24375316, 2014).
lung adenocarcinoma (8 papers, 2014 to 2025). A carcinoma that arises from the lung and is characterized by the presence of malignant glandular epithelial cells. "LRPPRC is also a prospective therapeutic target for lung adenocarcinoma, serving as a promising target for OXPHOS inhibition." (PMID 39744573, 2025). "It has been proven that LRPPRC promoted invasion, but inhibited apoptosis in prostate cancer, lymphoma, lung adenocarcinoma, and so on." (PMID 40775462, 2025). "Previous reports have showed that LRPPRC was highly expressed in most cancers, such as hepatoma cancer, lung adenocarcinoma, esophageal squamous cell carcinoma, colon cancer and lymphoma, and significantly associated tumorigenesis and invasion." (PMID 24375316, 2014). "Moreover, T-96 exhibited potent antitumor activity for lung adenocarcinoma in vitro and in vivo, and the antitumor effect of T-96 was dependent on LRPPRC expression." (PMID 39744573, 2025). "However, LRPPRC is upregulated in human lung adenocarcinoma, and knockdown of LRPPRC inhibits the growth of bladder and lung cancer cells in vitro and in vivo." (PMID 34671012, 2021). "Herein, we report that Leucine-rich pentatricopeptide repeat-containing (LRPPRC) protein can form a positive feedback loop with CDK6 to regulate CDK6 expression and CDK4/6i treatment response in lung adenocarcinoma (LUAD)." (PMID 37452037, 2023). "Transcriptome data from the TCGA database showed that the RNA level of LRPPRC was positively correlated with that of CDK6 (n = 515, Rho = 0.327, P < 0.0001) and E2F1 (n = 515, Rho = 0.383, P < 0.0001) in lung adenocarcinoma; and the positive correlation tendency was widespread in different tumors." (PMID 37452037, 2023). "Of the 16 distinguishing proteins, 8 were significantly elevated in lung adenocarcinoma (COPG1, STOML2, HYOU1, PDIA4, EPRS, APEX1, LRPPRC and NANS) whereas 8 proteins were significantly decreased in lung adenocarcinoma (SPTB, SPTA1, ANK1, SLC4A1, HBG1 and HBG2)." (PMID 27799870, 2016). "As LRPPRC is an emerging protein biomarker and a promising therapeutic target for the most lethal PP subtype of LUAD22, we hypothesized that T-96 could be a candidate drug for the treatment of lung adenocarcinoma." (PMID 39744573, 2025).
lung carcinoma (8 papers, 2021 to 2025). "Various studies demonstrate that high expression of LRPPRC is associated with poor prognosis in a variety of malignancies, such as bladder urothelial carcinoma, lung cancer and pancreatic cancer." (PMID 37700277, 2023). "Here, we demonstrate that Leucine Rich Pentatricopeptide Repeat Containing (LRPPRC) controls CDK4/6i response in lung cancer by forming a feedback loop with CDK6." (PMID 37452037, 2023). "In vivo tumorigenic experiments showed that LRPPRC-/- cell completely lost the tumorigenic ability, indicating LRPPRC was necessary for lung cancer stem cells maintainance." (PMID 37452037, 2023). "While previous studies have shown that GAA affects the stability of the LRPPRC protein in lung cancer cells, its therapeutic value in ovarian cancer is yet to be ascertained." (PMID 37496051, 2023). "Flow cytometry analysis showed a significant decrease in lung cancer CSC marker CD133 after LRPPRC knockout 45,46." (PMID 37452037, 2023). "We also looked at the protein levels of RBMX, METTL16, and LRPPRC in lung cancer cells and discovered that RBMX and LRPPRC were upregulated, whereas METTL16 was downregulated in lung cancer cells relative to normal lung epithelial cell BEAS-2B." (PMID 35035657, 2022).
ovarian carcinoma (7 papers, 2014 to 2025). A malignant neoplasm originating from the surface ovarian epithelium. "The findings of this study indicate that the cuproptosis process in ovarian cancer, induced by Elesclomol, is associated with mitochondrial complex IV, with LRPPRC identified as a crucial factor." (PMID 41516324, 2025). "Based on the somatic mutation data of 17301 genes from 316 ovarian cancer patients from The Cancer Genome Atlas, mutations in both LRPPRC and MAP1S were found to reduce the survival of patients." (PMID 24722279, 2014). "Next, to determine if SDHA or LRPPRC depletion affects each other’s protein expression, we knocked down (KD) either SDHA or LRPPRC in several mouse and human ovarian cancer cell lines." (PMID 40563592, 2025). "Following the knockdown of LRPPRC in two ovarian cancer cell types, we observed a reduction in the expression of chaperone proteins SCO1 and SCO2, with a more pronounced decrease in SCO1." (PMID 41516324, 2025). "The results revealed that LRPPRC was significantly upregulated in these tissues, indicating its potential as a target for inducing cuproptosis in ovarian cancer." (PMID 41516324, 2025). "Specifically, SDHA and LRPPRC expression was significantly lower in normal FT when compared with ovarian cancer." (PMID 40563592, 2025). "Lastly, we demonstrated that shikonin treatment in vitro leads to a loss of OXPHOS activity, bioenergetic dysfunction, and death of SDHA- and LRPPRC-overexpressing ovarian cancer cell lines." (PMID 40563592, 2025). "Inhibition of the IV-stabilizing protein LRPPRC in the ovarian cancer cell lines A2780 and SKOV3 through RNA interference resulted in increased sensitivity to Elesclomol." (PMID 41516324, 2025). "Our analysis of transcriptomics data showed that the tumor-specific upregulation of SDHA is accompanied by LRPPRC overexpression, particularly in advanced ovarian cancer." (PMID 40563592, 2025). "Our findings revealed a shift toward significantly higher gene expression of both SDHA and LRPPRC when precursor lesions progressed to advanced ovarian cancer." (PMID 40563592, 2025). "In alignment with these findings, we present new evidence that LRPPRC plays a role in promoting drug resistance in ovarian cancer cells through the regulation of the cuproptosis pathway." (PMID 41516324, 2025). "Knockdown of LRPPRC in ovarian cancer cells is believed to impact the assembly of complex IV by decreasing SCO1, while simultaneously affecting the biosynthesis of complex IV through the downregulation of FDX1 and lipoic acidylated proteins." (PMID 41516324, 2025). "We initially assessed the expression of LRPPRC, a protein that stabilizes complex IV mRNA and facilitates protein translation, in ovarian cancer tissues." (PMID 41516324, 2025). "Next, we measured SDHA and LRPPRC protein expression in mouse and human ovarian cancer cell lines, HGSOC PDXs, and normal hFTs using WES(ProteinSimple) and observed a concomitant SDHA and LRPPRC protein expression in all examined tissues." (PMID 40563592, 2025). "Our Seahorse-based assays showed that LRPPRC plays an essential role in promoting OXPHOS in SDHA-overexpressing ovarian cancer cell lines." (PMID 40563592, 2025). "PSMD14 inhibits autophagy and thus influences the progression of ovarian cancer through the LRPPRC/Beclin1-Bcl-2/SQSTM1 signaling pathway." (PMID 40182048, 2025). "Overall, we strive to advance scientific knowledge by highlighting the understudied role of SDHA and LRPPRC in ovarian cancer and their potential utility as biomarkers of high-OXPHOS tumors to guide personalized cancer therapy." (PMID 40563592, 2025). "Our analysis of SDHA and LRPPRC gene and protein expression patterns in precursor lesions and established ovarian cancer demonstrated that the upregulation of SDHA is accompanied by LRPPRC overexpression, notably in advanced tumors." (PMID 40563592, 2025).